GLI1 (GLI family zinc finger 1)
Diseases named in the same sentence as GLI1 in open-access papers (continued):
Sharing a sentence is not in itself a finding about the gene and the disease.
pancreatic cancer (continued). "Moreover, in previous studies we have proposed the hypothesis that S100A4 gene might be one of the key factors in EMT molecular network regulated by Shh-Gli1 signaling pathway in pancreatic cancer cells." (PMID 25072505, 2014). "Additionally, GLI1 siRNA significantly abolished pancreatic cancer invasion induced by hypoxia." (PMID 23786654, 2013). "Our study reveals that Gli1 maintained cell survival by binding the promoter regions and facilitating transcription of IGFBP6 and Bcl-2 genes in a parallel manner in pancreatic cancer cells and suggests it may be one of the mechanisms of Shh-Gli1 signaling pathway in pancreatic cancer." (PMID 19736394, 2009). "Gemcitabine-resistant pancreatic cancer cells display a higher expression of SHH, SMO, and GLI1 in comparison with parental cells." (PMID 35154464, 2022). "In support of this notion, two prior studies showed that Gli1 induces SOX2 expression in melanoma and pancreatic cancer through a cis-element in the SOX2 promoter." (PMID 33499351, 2021). "For instance, in a model of pancreatic cancer, SMO-independent Gli1 activation promotes transformation and requires both TGF-β and KRAS signaling." (PMID 31244888, 2019). "For example, the hedgehog transcription factor Gli1 targets the epigenetic modifiers DNMT1 and DNMT3a, which are positive targets of oncogenic epigenetic pathways in pancreatic cancer." (PMID 30060755, 2018). "Gli1 expression in pancreatic cancer cells upregulates S100A4 and the Shh-Gli1 signaling pathway facilitates pancreatic cancer metastasis by the promotion of S100A4 gene transcription." (PMID 29069865, 2017). "Treatment with BAY ACC002 (30 mg/kg/day for 7 days p.o.)in a Capan-2 pancreatic cancer xenograft mouse model suppressed mRNA expression of the WNT/β-catenin target gene AXIN2 by ∼60% and of the HH target gene GLI1 by 40%." (PMID 27750213, 2017). "For example, α-mangostin inhibits hypoxia-driven ROS-induced aggression against pancreatic cancer cells by reducing ROS production, which leads to inhibition of HIF-1α stabilization, GLI1 expression, and EMT." (PMID 28537893, 2017). "To confirm that GLI is indeed the important and key molecules to maintain CSC-like properties of pancreatic cancer cells, we knocked down GLI1 in Capan-1 M9 cells." (PMID 27349387, 2016). "In pancreatic cancer, TGFβ/SMAD signaling is able to induce expression of GLI activator forms and in Ewing Sarcoma the EWS-FLI1 oncogene directly stimulates GLI1 expression." (PMID 26784250, 2016). "In the pancreatic tumor microenvironment, KRAS mutant cancer cells induced the expression of GLI1 in surrounding fibroblasts, followed by the binding of GLI1 to the cytokine interleukin (IL)-6 promoter inducing its expression." (PMID 26633513, 2015). "All pancreatic cancer cell lines except SW1990 express readily detectable levels of GLI1 protein, similar results of the GLI1 mRNA levels in these cell lines were detected using qRT-PCR." (PMID 23786654, 2013). "In Pancreatic cancer model, we also observed that GLI2 had higher number of downstream activated proteins compared to GLI1 as it had an activation effect on GLI1, although the Eigenvector centrality of GLI2 was low compared to GLI1." (PMID 23935937, 2013). "SFN inhibited the expression of Smo, Gli1 and Gli2 in these cell lines as well, suggesting that SFN can inhibit the activation of Shh signaling in pancreatic cancer." (PMID 23029396, 2012). "Our results highlight the critical role of SHH signaling in human pancreatic CSCs and the possibility of targeting Gli1 and Gli2 activator functions using GDC-0449 in pancreatic cancer stem cells." (PMID 22087285, 2011). "QRT-PCR was performed to evaluate the levels Shh, Gli1, IGFBP6, IGF2, PCNA, Bcl-2, Bax and Bak1 mRNA in pancreatic cancer tissues (n = 6) and corresponding cancer side tissues (n = 6)." (PMID 19736394, 2009). "In conclusion, Gli1 directly facilitates expressions of IGFBP6 and Bcl-2 at the same time in cultured pancreatic cancer cells." (PMID 19736394, 2009).
pancreatic cancer (continued). "Gli1 activation in these cells was inhibited by Smo knockdown with short interfering RNA, indicating the potential of targeting Smo as a therapeutic approach to interfere with the pro-tumorigenic SHH signaling in the microenvironment of pancreatic cancer." (PMID 39900571, 2025). "The key transcriptional factor in the Hedgehog signaling pathway, GLI family zinc finger 1 (GLI1) bound to REG4 promoter regions (GATCATCCA) for its transcription and translation in pancreatic cancer cells, supported by the synergic expression of REG4 and GLI1." (PMID 36172286, 2022). "Notably, the GLI family of HH transcription factors (GLI1, GLI2, GLI3), remain largely unexplored in pancreatic cancer." (PMID 35867772, 2022). "GLI1 expression has also been reported to be regulated by PI3K/AKT/mTOR signaling in several other cancers to promote tumorigenesis, including esophageal adenocarcinoma, melanoma, osteosarcoma, pancreatic cancer, ovarian cancer, and renal cancer." (PMID 34572373, 2021). "The PI3K-AKT-mTOR signaling pathway is another crucial non-canonical activator of GLI1, particularly evident in pancreatic cancers." (PMID 34113570, 2021). "Lineage-tracing experiments revealed that GLI1-positive cells, but not Hoxb6-positive cells, which proliferated and promoted the fibrotic reaction in pancreatic cancer." (PMID 33333727, 2020). "Down-regulation of GLI1, GLI2 or SOX2 sensitized pancreatic cancer cells to gemcitabine treatment." (PMID 30382189, 2019). "Further studies are needed to test whether GLI1/2 inhibitors, including GANT61, are effective in reducing drug resistance in pancreatic cancer." (PMID 30382189, 2019). "Consistently, in pancreatic cancer cells KRAS has been shown to increase GLI1 activity via MEK1/2-ERK1/2, and KRAS-mediated activation of GLI1 is suppressed with UO126, through decrease of GLI1 protein stability." (PMID 30934935, 2019). "Besides that, sonic hedgehog (SHH)/GLI1 expression induced a significant upregulation of expression level of S100A4, a member of the S100 gene family and a key EMT molecular marker in pancreatic cancer, while E-cadherin was markedly reduced." (PMID 31547193, 2019). "And the interaction of ITGB4 promoter with some transcription factors in other disease is also reported, such as KLF4 in glioma 21, RUNX1 in myeloid leukemia 22, ZEB1 in prostate cancer 23, TP73 in lung cancer 24, GLI1 in ovarian cancer 25, and JUN in pancreatic cancer." (PMID 31602273, 2019). "We have evidence to show that inhibition of K-RAS downstream effector MEK signaling by AZD6244, but not the PI3K signaling by BEZ235, reduced Hh target gene GLI1 expression in pancreatic cancer cells." (PMID 30373214, 2018). "Likewise, it decreased expression of another HH/GLI1 target gene, Secreted frizzled-related protein 1 (SFRP1), which was upregulated in pancreatic cancer." (PMID 27750213, 2017). "Although the direct crosstalk between Gli1 and EMT is not completely elucidated, it is known that Gli1 exhibits a pro–tumorigenic effect on pancreatic cancer cells by altering the EMT process." (PMID 26988754, 2017). "Pancreatic cancer cells have been shown to express GLI1 in response to TGFβ and RAS signaling independent of SMO activation." (PMID 26784250, 2016). "To test whether DYRK1B contributes to the control of GLI1 expression in pancreatic cancer cells, we analyzed PANC-1 cells for GLI1 expression in response to DYRK1 inhibition." (PMID 26784250, 2016). "In agreement with the previous data in SUFU-deficient and pancreatic cancer cells, inhibition of DYRK1B but not of DYRK1A reduced GLI1 protein levels." (PMID 26784250, 2016). "Three typical cell lines of pancreatic cancer (PANC 1, MIA PaCa-2, and Capan-1) and one subline established in our laboratory (Capan-1 M9, see 3.2) showed positive staining with anti-SHH and anti-GLI1 antibodies." (PMID 27349387, 2016).
pancreatic cancer (continued). "Moreover, we attempted to identify new connections of Shh-Gli1 signaling pathway with S100 genes family and to demonstrate pro-metastatic function of S100A4 gene mediated by Shh-Gli1 signals in pancreatic cancer." (PMID 25072505, 2014). "Our data establish a novel connection between Shh-Gli1 signaling and S100A4 regulation, which imply that S100A4 might be one of the key factors in EMT mediated by Shh-Gli1 signaling in pancreatic cancer." (PMID 25072505, 2014). "Moreover, immunohistochemistry result suggested the expressions of GLI1, DNMT1, and DNMT3a in pancreatic cancer tissues were higher than those in adjacent normal tissues." (PMID 24822169, 2014). "Finally, the expressions of Shh, Gli1, S100A4 and E-cadherin in pancreatic cancer tissues were studied by using immunohistochemistry assays." (PMID 25072505, 2014). "Our findings provide a new connection establishing between Shh-Gli1 signals and S100A4 gene, which could be a therapy target for pancreatic cancer." (PMID 25072505, 2014). "We first explored the expression of GLI1 and HIF-1α in six human pancreatic cancer cell lines." (PMID 23786654, 2013). "From our study we observed the under expressions of various oncoproteins in Hedgehog pathway while perturbing at a time the combinations of the proteins GLI1, GLI2 and SMO in Glioma; SMO, HFU, ULK3 and RAS in Colon cancer; SMO, HFU, ULK3, RAS and ERK12 in Pancreatic cancer." (PMID 23935937, 2013). "This is consistent with the observation that overexpression of constitutively active AKT2 not only failed to rescue Gli1 activity in pancreatic cancer cells lacking K-Ras, but also further decreased it, albeit not significantly." (PMID 23900341, 2013). "As a result, perturbation of SMO or PTCH1/PTCH2 receptors was not effective to reduce the activation of GLI1/GLI2/GLI3_A in pancreatic cancer model." (PMID 23935937, 2013). "Mutant K-ras signaling through Mirk/dyrk1B blocked autocrine Hedgehog signaling to Gli1 within pancreatic cancer cells, only allowing Hedgehog signaling to Gli1 in stromal cells, which do not have mutant K-ras." (PMID 21559261, 2011). "The elevation of GLI1 and GLI2 in holoclones suggests higher activity of Hedgehog signaling, which was consistent with the higher level of SHH expression in CD44+CD24+ESA+ cancer stem cells isolated from human primary pancreatic cancer specimens." (PMID 21826251, 2011). "In this study, we demonstrated that Gli1 protein bound to the promoters of IGFBP6 and Bcl-2 by XChIP-PCR assays, which suggested that Gli1 facilitates transcriptions of IGFBP6 and Bcl-2 in a parallel manner in pancreatic cancer cells." (PMID 19736394, 2009). "Interestingly, our results showed HIF1α and GLI-1 expressions were also regulated by EZH2, which is consistent to the previous reports that the similar regulatory role of EZH2 in HIF1α and GLI-1 expressions has been shown in lung and pancreatic cancer cells." (PMID 38664825, 2024). "Interestingly, ectopic GLI1 expression in KRAS-expressing mice enhanced IKBKE expression and nuclear RelA staining, and the knockdown of IKBKE expression in pancreatic cancer cell lines impaired their ability to grow in soft agar and induced apoptosis by caspase 3 cleavage." (PMID 34572373, 2021). "One such case is pancreatic cancer, where it has been demonstrated that the expression levels of the lncRNA GLI1-AS, located with negative polarity to the GLI-1 promoter, negatively correlate with the expression levels of GLI-1, showing that silencing of GLI1-AS promotes the overexpression of GLI-1." (PMID 28948003, 2017). "Having shown that GLI1 expression in PANC-1 cells depends on DYRK1B, we therefore addressed whether inhibition of DYRK1B is able to phenocopy the anti-tumorigenic effect of GLI1 inhibition in pancreatic cancer cells." (PMID 26784250, 2016). "Interestingly, inhibition of PI3K pathway by wortmannin partially increased Gli1 luciferase activity without affecting GLI1 mRNA levels in pancreatic cancer cells." (PMID 23900341, 2013).
pancreatic cancer (continued). "Here we verify in four distinct primary pancreatic cancer cell lines derived from patient tumors that cancer stem cell-enriched sphere cultures indeed show marked overexpression of SHH and the Hedgehog target genes GLI-1 and GLI-2, as well as increased mTOR pathway activity." (PMID 23825539, 2013). "Taken together, we found that elevated GLI1 and GLI2, but not the ligands SHH and IHH, is required for the acquired gemcitabine resistance in pancreatic cancer both in cultured cells and in mice." (PMID 30382189, 2019). "In agreement with the critical role of DYRK1B in GLI1 expression, RNA-interference against DYRK1B but not against DYRK1A inhibited clonogenic growth of GLI1-dependent pancreatic cancer cells." (PMID 26784250, 2016). "Since the blockade of GLI1 does not affect SMO expression, these data indicate that hypoxia facilitates pancreatic cancer cell EMT and invasion through increasing the transcription level of SMO." (PMID 23786654, 2013). "On the other hand, the expression of IGF2 was very low in pancreatic cancer and was not affected by cyclopamine or RNAi for Gli1, which means the regulation of IGF2 expression is independent of Shh-Gli1 signaling pathway in pancreatic cancer." (PMID 19736394, 2009). "Intriguingly, EMT conversion of pancreatic cancer cells occurred without up-regulation of Snail or Slug, two canonical inducers of EMT in many other settings, and GLI1 directly regulates E-cadherin transcription, a vital determinant of epithelial tissue feature." (PMID 23786654, 2013).
glioma (97 papers, 2010 to 2026). A benign or malignant brain and spinal cord tumor that arises from glial cells (astrocytes, oligodendrocytes, ependymal cells). "GLI1, a Hedgehog effector implicated in glioma proliferation and therapy resistance, was upregulated in males but downregulated in females in LGG vs. HGG." (PMID 41514565, 2025). "The aberrant activation of GLI1 has been associated with cancers such as glioma, osteosarcoma, and rhabdomyosarcoma." (PMID 39769147, 2024). "The targeting by TFs (see the sections “Methods”: “Applications of netZoo using the Cancer Cell Line Encyclopedia”) glioma-associated oncogenes 1 and 2 (GLI1 and GLI2) was also significantly increased in melanoma." (PMID 36894939, 2023). "When SMO is inactive, Suppressor of Fused (SUFU) binds to the three GLI (from glioma-associated) zinc finger transcription factors (GLI1, GLI2, GLI3) and prevents their nuclear translocation and gene regulatory activities." (PMID 36769284, 2023). "COL1A1 is one of the downstream targets of the glioma-associated oncogenes (GLI1 and GLI2), is involved in collagen deposition, and is associated with PDAC aggression." (PMID 36038612, 2022). "Among these oncogenes, overexpression of NUAK2 promotes proliferation and invasion of A172,GLI1 is a well-known glioma-associated transcription factor; suppression of TMEM140 attenuates growth of glioma cell." (PMID 35521558, 2022). "Recently, it has been shown that PACAP significantly reduced glioma cells invasion in the rat brain parenchyma by blocking sonic hedgehog-GLI1 (Shh/GLI1) pathway, another signaling cascade implicated in tumor progression." (PMID 34440169, 2021). "Glioma-associated oncogenic (Gli) proteins are the main effectors of the Shh pathway, including Gli1, Gli2 and Gli3." (PMID 31901237, 2020). "Hh-dependent cancers are often driven by activating mutations that occur downstream of Smo and directly activate the transcription factors known as glioma-associated oncogenes (Gli1-3)." (PMID 31137846, 2019). "In the presence of Hh, the repressive action of PTCH1 on SMO is removed and the downstream pathway is mediated via the glioma-associated zinc transcription factors, Gli1 and Gli2, which translocate to the nucleus and activate Hh-target genes." (PMID 29423837, 2018). "Expression of Patched 1 (PTCH1), Smoothened (SMO), and glioma-associated zinc transcription factors (Gli1 and Gli2) were assessed in histological sections using immunohistochemistry and immunofluorescence (IF) techniques." (PMID 29423837, 2018). "In vitro, studies showed that the expression of glioma-associated zinc finger transcription factor 1 (Gli1) was decreased at both transcriptional and translational levels after treatment with itraconazole." (PMID 28399898, 2017). "Additionally, GLI1, a key transcription factor in the HH pathway, has been implicated in the maintenance of glioma stem cells, which are known to contribute to tumor recurrence and therapeutic resistance." (PMID 41596413, 2026). "The aberrant activation of GLI1 has been linked to the promotion of oncogenic activities such as metastasis, DNA damage repair, stemness, and chemotherapeutic resistance in various cancers such as glioma, pancreatic cancer, and colorectal cancer." (PMID 39769147, 2024). "Moreover, GLI2 expression has been strongly linked to many types of glial tumors, including astrocytomas, gangliogliomas, glioblastomas, ependymomas, and oligodendrogliomas, whereas GLI1 and 3 correlated preferably with oligodendrogliomas." (PMID 35409080, 2022). "Activation of PI3K/AKT pathway and SHH/Gli1 pathway is associated with glioma progression." (PMID 36056982, 2022). "There are three glioma-associated oncogenes (GLI) transcription factors, GLI1, GLI2 and GLI3." (PMID 29298879, 2018).